TFEB (transcription factor EB)
Diseases named in the same sentence as TFEB in open-access papers (continued):
Sharing a sentence is not in itself a finding about the gene and the disease.
heart failure (9 papers, 2019 to 2025). Inability of the heart to pump blood at an adequate rate to meet tissue metabolic requirements. "Adeno Associated Viral vectors (AVV)-mediated TFEB overexpression was found to attenuate autophagic blockade, cardiomyocyte death, and heart failure in MAO-A transgenic mice." (PMID 37188688, 2023). "To investigate if the heart failure phenotype resulting from TFEB overexpression was associated with increased interstitial myocardial fibrosis, we performed Picrosirius Red staining of histological cross-sections from our experimental groups." (PMID 35682624, 2022). "Rapamycin alleviates heart failure via TFEB and CaMKII pathways in Syntaxin 12/13 deficient models." (PMID 40568929, 2025). "Since we have also only investigated male mice, further studies are needed to address sex-based differences in the effects of TFEB-induced ALP activity in heart failure." (PMID 35682624, 2022). "Cardiomyocyte-specific TFEB overexpression sensitizes the heart to pressure-overload-induced cardiac stress resulting in heart failure." (PMID 35682624, 2022). "In summary, our data show that cardiomyocyte-specific overexpression of TFEB promotes the expression of ALP genes during TAC, which was associated with the occurrence of heart failure in response to pressure-overload." (PMID 35682624, 2022). "Our data suggest that TFEB sensitizes the heart to hemodynamic stress and facilitates heart failure possibly due to the activation of ALP-mediated protein degradation." (PMID 35682624, 2022). "Cardiomyocyte-specific TFEB-overexpression promoted ALP gene expression during TAC, which was associated with heart failure." (PMID 35682624, 2022). "TFEB overexpression can alleviate the accumulation of autophagosomes, mitochondrial division, and myocardial cell death in heart failure." (PMID 32071922, 2020). "A study has shown that miR-342-3p can target and downregulate the expression of SOX6 and TFEB, thereby inhibiting myocardial cell apoptosis and autophagy, and exerting a protective effect on myocardial cells in mice with heart failure induced by myocardial infarction." (PMID 40997050, 2025). "We found that cardiomyocytes-specific overexpression of TFEB resulted in heart failure as indicated by left ventricular dilatation, reduced systolic function, increased the expression of stress response genes, augmented interstitial fibrosis and pulmonary congestion." (PMID 35682624, 2022). "Moreover, doxorubicin damages lysosomal function, resulting in the incomplete execution of the transcription factor EB (TFEB)‐driven autophagy programme, the obstruction of autophagosome‐lysosomal fusion, causing left ventricular atrophy and heart failure, and ultimately increasing mortality." (PMID 40785055, 2025).
liver disease (9 papers, 2013 to 2024). "TFEB gene transfer is a novel strategy for liver disease in SERPINA1 deficiency and prevent accumulation of toxic proteins." (PMID 34830348, 2021). "Using adenovirus-mediated gene transfer of TFEB in the PiZ mouse model of ATD-associated liver disease, they found that TFEB transfer promoted hepatic ATZ clearance and reduced liver fibrosis in the mice." (PMID 24719116, 2014). "Nevertheless, the results of the present study illustrate the great potential of TFEB gene transfer, or possibly of pharmacological approaches resulting in TFEB activation, for therapy of liver disease caused by hepatotoxic ATZ." (PMID 23381957, 2013). "Liver injury in patients with AAT deficiency is a direct consequence of hepatic accumulation of polymerized ATZ and therefore, TFEB gene transfer has tremendous potential for the treatment of liver disease in patients with AAT deficiency." (PMID 23381957, 2013). "In conclusion, TFEB gene transfer is a novel strategy for treatment of liver disease of alpha-1-anti-trypsin deficiency." (PMID 23381957, 2013). "In conclusion, our study shows the efficacy of TFEB gene transfer for therapy of liver disease of AAT deficiency by ATZ disposal through the autophagolysosome system." (PMID 23381957, 2013). "In this aggressive liver disease setting, loss of Flcn led to activation of transcription factors TFEB and TFE3 to promote autophagy, promoting the degradation of intracellular lipid stores, ultimately resulting in reduced hepatocellular damage and inflammation." (PMID 34711912, 2021). "The results of our study could suggest that genetically determined differences in the level of activity of the TFEB-autophagy-lysosome axis may play a role in favouring or protecting from the development of liver disease in AAT deficiency." (PMID 23381957, 2013). "In this review, we will present the regulation of TFEB and its role in the pathogenesis of liver diseases, particularly non-alcoholic fatty liver disease (NAFLD)." (PMID 35625599, 2022). "In this review, we will present the regulation of TFEB and its role in the pathogenesis of liver disease, particularly non-alcoholic fatty liver disease (NAFLD)." (PMID 35625599, 2022). "In the present study, we have investigated a novel strategy to correct the hepatic disease of AAT deficiency, based on clearance and prevention of ATZ accumulation by TFEB gene transfer." (PMID 23381957, 2013). "Besides, owning to the effect on autophagy, TFEB was reported to involve in the development and progression of liver disease." (PMID 36224178, 2022). "We investigated the therapeutic potential of liver-directed gene transfer of transcription factor EB (TFEB), a master gene that regulates lysosomal function and autophagy, in PiZ transgenic mice, recapitulating the human hepatic disease." (PMID 23381957, 2013).
neuroblastoma (9 papers, 2019 to 2025). Neuroblastoma (NB) is the most common solid, extracranial childhood tumor. "The activation of the PERK-Ca2+-calcineurin axis by SB202190 positively affects TFEB activity to increase ALP in neuroblastoma cells." (PMID 35166693, 2022). "Similar effects of C1 on lysosomal glycohydrolase expression and their recruitment to lipid microdomains was observed by treating the SH-SY5Y neuroblastoma cell line; the effects of C1 treatment were abolished by TFEB silencing." (PMID 30889901, 2019). "The treatment of the neuroblastoma cell line SH-SY5Y with the curcumin analogue C1 also promoted TFEB nuclear translocation and the increase of lysosomal glycohydrolase expression and activity and their recruitment to the cell surface." (PMID 30889901, 2019). "Therefore, we propose that CO can promote TFEB nuclear translocation to activate autophagy in SH-SY5Y human neuroblastoma cells." (PMID 40425550, 2025). "In this study, we utilized the human neuroblastoma cell line SH-SY5Y to establish pharmacological models of Gaucher, NPA, and NPC diseases, enabling the evaluation of c-Abl/TFEB pathway activation and its impact on lysosomal clearance." (PMID 40427492, 2025). "Here, we analyze the effects of the broad-spectrum HDAC inhibitors (HDACi) panobinostat and vorinostat on the transcriptional regulation of autophagy with respect to autophagy transcription factor activity (Transcription factor EB—TFEB, forkhead boxO—FOXO) and autophagic flux in neuroblastoma cells." (PMID 33923163, 2021). "Moreover, we did not observe nuclear translocation of TFEB, a master transcription factor of autophagy and lysosomal genes, after broad-spectrum HDACi treatment of neuroblastoma cells." (PMID 33923163, 2021). "Moreover, by using the SH-SY5Y neuroblastoma cell line, we confirmed the ability of the curcumin analogue C1 to activate TFEB without inhibiting mTORC1 activity, thus suggesting its potential therapeutic efficacy for the treatment of neurodegenerative diseases by promoting autophagy." (PMID 30889901, 2019).
non-alcoholic fatty liver disease (9 papers, 2020 to 2025). "The mechanisms underlying the protective influence of trehalose include activation of hepatic transcription factor EB (TFEB); it was reported that trehalose protects against diet-induced nonalcoholic fatty liver disease in mice." (PMID 35330193, 2022). "TFEB also contributes to being a potential therapeutic target for non-alcoholic fatty liver disease via the beneficial effect in regulating lipolysis and lipophagy." (PMID 33679452, 2021). "This is substantiated by studies demonstrating that TFEB inhibition abolishes lipophagy and makes for the decomposition of cellular lipid in anti-non-alcoholic fatty liver disease." (PMID 33679452, 2021). "Recently, hepatic TFEB overexpression has been shown to protect against non-alcoholic fatty liver disease (NAFLD) and alcoholic liver disease in mice." (PMID 32681035, 2020). "On the other hand, enhanced activation of TFEB may be desirable in treating lysosomal storage disorders, promoting clearance of toxic aggregates and debris in neurons and preventing non-alcoholic fatty liver disease through lipid clearance." (PMID 36697823, 2023).
Batten disease (8 papers, 2017 to 2025). "Overexpression of TFEB reduces the accumulation of lipofuscin in cell models derived from mice and patients with Batten disease, which is caused by mutations of the CLN3 gene." (PMID 33292395, 2020). "TFEB overexpression also promotes clearance of lipofuscin in fibroblasts from patients with Batten’s disease, a form of NCL51." (PMID 40683940, 2025). "The effect of tamoxifen in Batten disease is mediated by its action on transcription factor EB (TFEB), a master regulator of the lysosomal function in cells, which promotes the clearance of pathological storage in different LSDs." (PMID 38540351, 2024). "Trehalose activates TFEB via Akt inhibition and enhances cellular clearance to reduce neuropathology in Batten disease." (PMID 33292395, 2020).
cystinosis (8 papers, 2019 to 2025). Cystinosis is a metabolic disease characterized by an accumulation of cystine inside the lysosomes, causing damage in different organs and tissues, particularly in the kidneys and eyes. "Several mechanisms have been suggested to contribute to the pathogenesis of cystinosis, including lysosomal overload, endo-lysosomal transport defect, altered chaperone-mediated autophagy, mTOR signaling, transcription factor EB (TFEB) expression." (PMID 31888107, 2019). "Furthermore, in vivo cystinosis studies reported abnormal levels of autophagy, with changes in the expression of key autophagy genes such as TFEB, LC3II, and SQSTM1." (PMID 35011739, 2022). "In addition to lysosomal cystine storage, cellular dysfunctions, such as abnormal vesicular trafficking, autophagy, apoptosis, and TFEB (Transcription Factor EB) signaling, have also been described as responsible for the pathogenesis of cystinosis." (PMID 34943781, 2021). "Taken together, cystinosis results from the reduction in expression and activity of TFEB and regulating TFEB may be a potential therapeutic strategy against cystinosis." (PMID 32377395, 2020).
glioblastoma (8 papers, 2017 to 2025). The most malignant astrocytic tumor (WHO grade IV). "In fact, drug-mediated inhibition of TFEB expression and oligomerization can enhance glioblastoma cell sensitivity to conventional chemotherapeutic agents." (PMID 35665902, 2022). "In glioblastomas, metabolic stress can inhibit the mechanistic target of rapamycin complex 1 (mTORC1) and reduce TFEB phosphorylation, which in turn reduces the amount of TFEB bound to 14-3-3." (PMID 35740562, 2022). "In glioblastoma, inhibition of TFEB resulted in the death of tumor cells due to its incapacity of withstanding growing metabolic pressure." (PMID 34490237, 2021). "It has been reported that TFEB is overexpressed in glioblastoma, along with other genes that codify for autophagic proteins, such as LC3A, LC3B, Beclin 1, Ulk 1, Ulk 2, p62, and SQSTM1." (PMID 32707662, 2020). "Moreover, increased TFEB expression is found in glioblastoma patients and contributes to the glioblastoma resistance to chemotherapy." (PMID 35665902, 2022). "Furthermore, numerous glioblastoma patients have shown an overexpression of autophagy-associated proteins with amplification of ULK1/ULK2 and transcription factor EB (TFEB)." (PMID 33525678, 2021). "Additionally, an overexpression of autophagic-related proteins has been observed in a high proportion of glioblastoma patients, with a significant increase of ULK1/ULK2 and TFEB." (PMID 32707662, 2020).
kidney cancer (8 papers, 2016 to 2025). Primary or metastatic malignant neoplasm involving the kidney. "This study provides direct evidence that overexpression of TFEB in the kidney is able to generate a severe cystic pathology associated with the development of kidney cancer and liver metastases, thus mimicking the cancer phenotype associated with human TFE-fusion ccRCCs chromosomal translocations." (PMID 27668431, 2016). "The larger collection of non-type-I papillary RCCs is composed of type II papillary renal carcinomas, including duct carcinomas, medullary renal cell carcinomas, the MiTF kidney cancers (TFE3, TFEB), and hereditary leiomyomatosis RCC-associated kidney cancers." (PMID 33205131, 2020). "In cases of rare kidney cancers, such as TFEB rearranged RCC, the small number of published cases and the limited knowledge of the molecular landscape and the genetic profile of the disease has limited the possibility of developing targeted drugs and selective compounds." (PMID 36830782, 2023). "TFEB and MITF mutations have also been noted in kidney cancers, albeit more rarely." (PMID 35358174, 2022). "An extensive molecular and biochemical characterization of kidneys, as well as of primary kidney cells, derived from these mice revealed a significant hyper-activation of the WNT pathway, suggesting that this signalling pathway plays an important role in TFEB-driven kidney cancer." (PMID 27668431, 2016). "Interestingly, TFEB and FNIP are both key mediators in unique forms of kidney cancer that often have an oncocytic phenotype (translocation RCC and Birt–Hogg–Dube (BHD) kidney cancer)." (PMID 40806782, 2025). "In addition, silencing of either TFEB or TFE3 rescued tumorigenesis in mouse xenografts generated using a cell line derived from a kidney cancer patient with BHD syndrome, indicating that TFEB and TFE3 are the main drivers of tumorigenesis in multiple tissues." (PMID 40189703, 2025).
microphthalmia (8 papers, 2016 to 2025). Congenital or developmental anomaly in which the eyeballs are abnormally small. "Transcription factor EB (TFEB), which is a member of the Microphthalmia family of bHLH-LZ transcription factors (MiT/TFE), is a master regulator of lysosome biogenesis and autophagy gene expression." (PMID 37653033, 2023). "Transcription factor EB (TFEB) belongs to the Microphthalmia/TFE family of leucine zipper transcription factors." (PMID 37601043, 2023). "The Microphthalmia-associated transcription factor family includes the basic helix-loop-helix domain-containing transcription factors MITF, TFE3, TFEB, and TFEC." (PMID 35842725, 2022). "Members of the Microphthalmia-associated transcription factor family (MiT), including MITF, TFE3 and TFEB, play a central role in regulating cellular homeostasis in response to metabolic pressure and are considered master regulators of lysosomal biogenesis." (PMID 35842725, 2022). "Translocation RCC, or microphthalmia-associated transcription factor family translocation RCC (MiTF-tRCC), encompasses a rare group of diseases involving translocations affecting the short arm of the X chromosomes and fusions of the TFE3, TFEB, or MITF genes." (PMID 40361453, 2025).
Multiple sulfatase deficiency (8 papers, 2013 to 2025). "Overexpression of TFEB in neuronal stem cells from a mouse model of multiple sulfatase deficiency mice resulted in a profound reduction in glycosaminoglycans levels and the restoration of normal cellular morphology." (PMID 36142486, 2022). "In multiple sulfatase deficiency (MSD) and mucopolysaccharidosis type IIIA (MPS-IIIA), two glycosaminoglycan (GAG) storage LSDs, TFEB overexpression was sufficient to reduce lysosomal GAG accumulation." (PMID 38451235, 2024). "Similarly, lysosomal exocytosis and reduction in cellular vacuolization occur after TFEB overexpression in various cell and mouse models of LSDs, including multiple sulfatase deficiency (MSD) and mucopolysaccharidosis type IIIA (MPS-IIIA) where a block in autophagy was previously reported." (PMID 29233882, 2017). "In another study, Sardiello and colleagues investigated the subcellular localization of TFEB in embryonic fibroblast from mouse models of three LSDs: mucopolysaccharidoses types II and III (MPSII, MPSIII) and multiple sulfatase deficiency (MSD)." (PMID 35665902, 2022). "Overexpression of TFEB induced lysosomal exocytosis in a mouse model of multiple sulfatase deficiency (MSD) and in cells derived from the murine models of mucopolysaccharidosis type IIIA (MPS-IIIA), neuronal ceroid lipofuscinoses, and MSD." (PMID 23606558, 2013).
myocardial infarction (8 papers, 2021 to 2025). Gross necrosis of the myocardium, as a result of interruption of the blood supply to the area, as in coronary thrombosis. "Although not fully understood, macrophage TFEB inhibition of inflammasomes and IL-1β secretion were also observed in previous studies within atherosclerotic and post-myocardial infarction mice models." (PMID 35228523, 2022). "Following a myocardial infarction, elevated TFEB boosted the expression of autophagy-related genes in ECs, boosting angiogenesis, and cardiac function recovery." (PMID 35600331, 2022). "TFEB is expressed in adult myocardium, and its expression is modulated during myocardial infarction." (PMID 34356609, 2021). "In this study, we first identified regulatory variants in the TFEB gene promoter in patients with acute myocardial infarction (AMI) and then functionally analyzed the effect of the variants on TFEB gene expression." (PMID 33732699, 2021). "miRNA-330-3p is downregulated, while TFEB is upregulated during myocardial infarction." (PMID 34356609, 2021). "Since dysfunctional autophagy plays critical roles in acute myocardial infarction (AMI), dysregulated TFEB gene expression may be associated with AMI by regulating autophagy." (PMID 33732699, 2021).
non-small cell lung carcinoma (8 papers, 2018 to 2025). A group of at least three distinct histological types of lung cancer, including non-small cell squamous cell carcinoma, adenocarcinoma, and large cell carcinoma. "A recent experiment has shown that sirtuin 2 (SIRT2) increases the mRNA stability of transcription factor EB (TFEB) and induces the release of exosomes to trigger autophagy and decrease apoptosis in non-small cell lung cancer cells." (PMID 35765040, 2022). "In non-small cell lung cancer (NSCLC), TFEB presence is associated with high levels of lysosomal markers and a poor prognosis." (PMID 32878084, 2020). "Next, we analyzed the role of TFEB in non-small cell lung cancer (NSCLC) using available databases." (PMID 40083935, 2025). "Overexpression of TFEB predicts poor prognosis of non-small cell lung cancer." (PMID 35965629, 2022). "In parallel, the overexpression of TFEB was significantly correlated with poor prognosis in non-small cell lung cancer (NSCLC), Silencing of TFEB with siRNA could reduce the migration, but not proliferation, of NSCLC cells." (PMID 29903018, 2018).
pancreatic ductal adenocarcinoma (8 papers, 2018 to 2024). An infiltrating adenocarcinoma that arises from the epithelial cells of the pancreas. "Overexpression of TFEB was reported to drive pancreatic ductal adenocarcinoma by inducing autophagy." (PMID 35970822, 2022). "TFEB levels were measured by real-time PCR, western blot and immunohistochemical staining in clinical pancreatic ductal adenocarcinoma tissues." (PMID 31387632, 2019). "Another study showed that miR-29a, which targets the ATG9A and TFEB mRNAs, is down-regulated in Pancreatic Ductal Adenocarcinoma (PDAC) leading to increased ATG9A levels, autophagy flux and resistance to gemcitabine, as well as increased cancer cell migration." (PMID 30563263, 2018).